CXCL8 (C-X-C motif chemokine ligand 8)
Diseases named in the same sentence as CXCL8 in open-access papers (continued):
Sharing a sentence is not in itself a finding about the gene and the disease.
viral infection (298 papers, 2005 to 2026). "CXCL8 (also referred to as IL-8), circulating chemokine, is associated with inflammation and immune cell trafficking in the context of viral infections." (PMID 33833618, 2021). "Our finding that the early post-viral infection response specifically triggers the production and secretion of CXCL8 prompted us to further investigate the role of CXCL8 in EV-D68 replication." (PMID 39962077, 2025). "There was also an unexpected downregulation of genes associated with viral infection and several inflammatory pathways, including TNF, chemokine, and IL‐17 signaling, (e.g., CXCL1 and CXCL8)." (PMID 39836544, 2025). "We validated this finding through RT-qPCR, confirming that the expression of the proinflammatory factors IL-1β, CCL4, TNF and CXCL8 decreased progressively with viral infection." (PMID 36544767, 2022). "Virus infection stimulated the production of inflammatory and antiviral mediators, including interleukin (IL)-6, CXCL-8, tumor necrosis factor (TNF)-α, and type I/III interferons." (PMID 35265536, 2022). "Virus infection induced a robust increase of IL-6, CXCL8, TNF-α, CXCL10, COX-2, and RANTES in mRNA level with a dose-dependent manner." (PMID 34552653, 2021). "CXCL8 expression can be stimulated by interleukin (IL) 6, TNFα, hypoxia and viral infection in cells such as monocytes, neutrophils, epithelial cells and fibroblasts." (PMID 33345622, 2021). "We selected IFNB1, IL6, and CXCL8 as markers of host response, representative of overlapping transcriptional responses to viral infection." (PMID 34357881, 2021). "We then quantified mRNA expression of IFN-β (type I IFN), IFN-λ (type III IFN), select ISGs (OAS2, IFIT1, IFIH1), and the neutrophil attracting chemokine IL-8 (CXCL8), which has been implicated in nasal inflammation during viral infection." (PMID 33811184, 2021). "While the basal levels of CXCL8 in uninfected cells remained unchanged over a period of three weeks, CXCL8 significantly increased as viral infection progressed from one week to three weeks in both HIV-1ADA - and HIV-1JRFL-infected MDM (p<0.001)." (PMID 24662979, 2014). "CXCR1 has recently been shown to be upregulated on hepatocytes in response to liver injury and CXCR1 positive CD8+ T cells responding to CXCL8 have been detected in different viral infections." (PMID 24646914, 2014). "Considering its affect on HIV-1 infection in macrophages and microglia, CXCL8 can be a potential therapeutic target for controlling persistence of viral infection in the brain." (PMID 24662979, 2014). "Corneal cells are reported to produce a variety of cytokines during response to viral infection including IL-1α, IL-6, CXCL8, and low levels of IFN-γ." (PMID 22518343, 2012). "Additionally, immunofluorescence analysis revealed that silencing the downstream signaling factor MEK1 or MEK2 within the CXCL8 pathway impeded the viral infection-induced translocation of the hnRNP-K protein to the cytoplasm." (PMID 39962077, 2025). "However, one limitation of this study is its lack of in vivo experimental data, which is primarily because the genomes of the mice commonly used for establishing viral infection models lack the CXCL8 coding sequence." (PMID 39962077, 2025). "However, the moderately expressed CXCL8 is known to be elevated in viral infections, producing protein known as interleukin-8." (PMID 38240884, 2024). "Our findings indicate that cilomilast may have the capacity to attenuate neutrophil accumulation at bronchial sites of acute virus infection, at least partially, via inhibition of CXCL8 production." (PMID 39598462, 2024). "The chemokine CXCL8, also known as the neutrophil chemotactic factor, plays a crucial role in mediating inflammatory responses and managing cellular immune reactions during viral infections." (PMID 38715098, 2024).
viral infection (continued). "The normal anti-viral response initially involves type I IFN elaboration from NK cells and CD8 + T-cells, ultimately killing infected cells and clearing the virus, whereas severe viral infections elicit IL-8/CXCL8 activation that promotes neutrophil chemotaxis, activation, and NET formation." (PMID 36289507, 2022). "An inflammatory reaction, critical to the efficiency of the immune response to viral infections, is characterized by the systemic release of specific cytokines and chemokines such as IL8/CXCL8 and by the chemotactic migration of leukocytes to the site of inflammation." (PMID 36611661, 2022). "The most down-modulated genes were related to T helper 2 pathway activation and induction of FOXP3 expression (AREG), immune tolerance (SMAD6), response to bacterial and viral infection and inflammation (CXCL8, PDE12, STX19, DFNB31), cell transport of glucose and organelles (KIF5A, SCL2A7)." (PMID 35058920, 2021). "The chemokine CXCL8 has been induced by viral infection, contributing to lung injury." (PMID 34733269, 2021). "The addition of SAPS liposomes at various times following viral infection suppressed the release of the proinflammatory cytokines, CXCL8 and CXCL10, as well as the interferon-stimulated gene CCL5/RANTES from epithelial cell lines and normal and diseased primary human bronchial epithelial cells." (PMID 26906404, 2016). "Expression of CXCL8 is not only induced by IL-1 or TNFα but also by viral infection or poly(I:C)." (PMID 24646914, 2014). "Therefore, our results establish that CXCL8 treatment increases nuclear transport of viral cDNA and promotes viral infection." (PMID 24662979, 2014). "In addition, the ability of T cells (which play an important role in viral infection) in premature neonates to produce C-X-C motif chemokine ligand 8 is insufficient, which may lead to serious complications and even adverse outcomes after infection." (PMID 39278913, 2024). "At the same time, the upregulation of IL1B and CXCL8, two pro-inflammatory cytokines involved in the innate immune response during the initial phases of viral infection, which could induce a good pro-inflammatory response to PVs, determining the clearance of the viral infection, was observed." (PMID 36016317, 2022). "Cytokines associated with lung injuries, such as IL-1 and TNF-α could induce the production of several chemokines, such as CCL2, CCL3, CCL5, and CXCL8, culminating in a cytokine-to-chemokine-to-cytokine signaling cascade through inflammatory response to the viral infection." (PMID 36685603, 2022). "However, if cytokine CXCL8 (interleukin-8) is present in the media during Ad5 infection, either due to co-culturing with macrophages on transwell inserts or using conditioned medium, virus infection occurs with high efficiency at the apical surface." (PMID 22355449, 2011). "The viral infection group exhibited significantly increased mRNA levels of IL-6, TNFα, CXCL-2, CXCL-3, CXCL-8/IL-8, and CXCL-10 compared to the NC group." (PMID 40872743, 2025). "Knockdown of YAP/TAZ or TEADs increased the transcriptional expression of antiviral and proinflammatory factors IFNB1, CXCL8 and IRF7 induced by virus infection." (PMID 35503798, 2022). "Chiefly amongst these, CCL3 (macrophage inflammatory protein-1α; MIP-1α), CCL4, CCL5, CXCL8, and CXCL10 are broadly expressed in the context of several (murine/human) viral infections." (PMID 34835105, 2021). "Inflammatory chemokines/cytokines, such as IL‐6, CXCL8/IL‐8, and IFN‐γ, are also released from circulating activated T cells, NK cells, monocytes, and tissue macrophages as a response to viral infection, again contributing to TMA development." (PMID 32643798, 2021). "Considering that interferon expression is mainly IRF3/IRF7-mediated while expression of TNFα and CXCL8 is mainly NFκB-mediated, it appears that azithromycin predominantly affects IRF signalling pathways after viral infection." (PMID 27350308, 2016).
viral infection (continued). "We found that neutrophils were able to respond, by means of CXCL8, NE and MMP‐9 release, to a variety of TLR agonists that mimic viral infections." (PMID 26477783, 2016). "Other cytokines and chemokines, including CXCL-8 (IL-8), CXCL-10 (IP-10), TGF-β and TNF-α protein, and type I IFN (IFN-β) and type III IFN (IFN-λ1) mRNA were increased to a similar extent during viral infection and co-infections with either of the PA isolates and HRV16." (PMID 35265536, 2022). "Upregulated expression of cytokines, chemokines and growth factors was commonly observed in patients and animals with lymphopenia induced by viral infection, including IL-2, IL-6, IL-12, IL-18, IL-1β, IFN-γ, CCL2/MCP-1, CXCL1, CXCL8/IL-8, CCL3/MIP-1-α, CCL7/MCP-3, CXCL10/IP-10 and CXCL9/MIG." (PMID 34578457, 2021). "CXCL8 mRNA and protein levels had a negative association with FEF25–75 independent of viral infection." (PMID 30463560, 2018). "Surprisingly, IV-induced pro-inflammatory cytokines and chemokines were substantially elevated after super-infection with S. aureus, while S. aureus-induced IL-1β and CXCL8 expression levels were not escalated by viral infection." (PMID 28195157, 2017). "Further, similar to the effects of dsRNA, infecting BSMCs with RV1B resulted in dose-dependent expression of CXCL8 mRNA whereas TNF-α expression was not appreciably affected after 24 h viral infection." (PMID 23658644, 2013). "In separate publications a group in Hong Kong reported that elevated levels of IL-6, CXCL8, CCL2, and sTNFR-1 correlated with severe cases of A(H1N1)pdm09 virus infection overall and, in particular, with the extent and severity of influenza-associated pneumonia." (PMID 23468921, 2013). "In this study, CXCL8 protein was significantly upregulated in DF-1 cells 48 h after DTMUV infection, with the highest fold change in expression, indicating that DTMUV infection induces CXCL8 expression in DF-1 cells, thereby alerting the host immune system to viral infection." (PMID 39772141, 2024). "In addition, several proinflammatory mediators are also induced, including cytokines (TNFα, IL-1β, IL-6, INF-λ1, INF-λ2), chemokines (CXCL6, CXCL8 (IL-8), CXCL10, and CX3CL1), and adhesion molecules (ICAM-1 and VCAM-1), which in turn promote immune cell recruitment to control the viral infection." (PMID 39337288, 2024). "CXCL8 could mediate productive infection of HIV-1 in cells via receptors CXCR1 and CXCR2 and also could be induced by Porcine epidemic diarrhea virus nsp4 which in turn inhibited virus infection." (PMID 35937300, 2022). "Numerous studies have already shown increased levels of IL6 and CXCL8 due to diesel exhaust or particulate matter exposure in primary respiratory cells, but not in the context of viral infections as reported in our study." (PMID 34542243, 2021). "On the other hand, virus infections trigger the production of inflammatory cytokines and chemokines in the respiratory tract including interleukin (IL)-6, chemokine (C-C motif) ligand 2 (CCL2), CCL5, CCL8, chemokine (C-X-C motif) ligand 8 (CXCL8), CXCL9, CXCL16, and CXCL2." (PMID 34578229, 2021). "In addition, levels of chemokines CXCL2, CXCL8, CXCL20 and CXCL14 were higher in men, which supports the hypothesis that the first stage of male response against a viral infection is typically related to inflammation and Th17 cell differentiation processes." (PMID 33271804, 2020). "Further, analysis of IL6 and CXCL8 expression corroborated a lack of active viral infection, as IL6 and CXCL8 are upregulated during acute infection." (PMID 41152229, 2025). "In the setting of treatment before viral infection, SAPS treatment did not significantly alter HRV-1B-induced CXCL8 and CCL5 production." (PMID 26906404, 2016). "Furthermore, we observed elevated levels of CXCL8 and CCL2 that promote the recruitment of non-adaptive immune cells to the liver such as monocytes, the main source of IL-15 and IL-18 during viral infections." (PMID 33617602, 2021).
viral infection (continued). "Indeed SAPS treatment before viral challenge with removal of liposomes immediately before viral infection further validates this conclusion, as it does not substantially diminish HRV-induced CXCL8 and CCL5 induction." (PMID 26906404, 2016).
Obesity (297 papers, 2009 to 2026). Accumulation of substantial excess body fat. "Elevated levels of IL-8 (CXCL8) in obesity have been linked with insulin resistance and type 2 diabetes (T2D)." (PMID 31443599, 2019). "Future studies will establish a potential synergy and the relative clinical importance of CXCL1 and CXCL8 in obesity-linked and progressive disease." (PMID 27241286, 2016). "Earlier studies have demonstrated that neutrophils secrete more CXCL8 after being activated by lipopolysaccharide (LPS) and N-Formyl-Met-Leu-Phe (fMLP), highlighting a potential link to the inflammatory response associated with obesity." (PMID 39334887, 2024). "Obesity, being associated with an increase in visceral fat, is characterized by low-grade inflammatory status with production of several of cytokines and chemokines such as beta-defensins 2/3, CXCL8/10, and CCL20, which promote the development of psoriasis." (PMID 35276950, 2022). "Furthermore, the middle-aged patients with the A/A and T/T genotypes in the CXCL8 gene (rs4073 and rs2227306, respectively) had a twofold decreased risk of obesity." (PMID 35207726, 2022). "Adiponectin can prevent the impairment of insulin signaling, so CXCL8 may plays a crucial and causal role in obesity-linked IR and GDM." (PMID 35211112, 2022). "Adiponectin can prevent the impairment of insulin signaling; hence CXCL8 may play a crucial and causal role in obesity-linked IR and T2DM." (PMID 34054797, 2021). "The researchers identified hypermethylation of the CXCL8 promoter region in peripheral blood samples from children with obesity compared to the control group." (PMID 40869388, 2025). "CXCL8, also known as IL-8, acts as a mediator of immune cell migration to sites of inflammation and is regarded as a critical factor in the development of early-onset obesity." (PMID 40869388, 2025). "Emerging research indicates that CXCL8 is critical in obesity pathophysiology, driving hepatic inflammation and damage through the chemotaxis of neutrophils and macrophages to the liver." (PMID 39334887, 2024). "Whole-genome transcriptome sequencing has identified the CXCL8 gene as playing a role in both individuals with obesity and those with metabolic impairments." (PMID 39334887, 2024). "Elevated levels of CXCL8 have been observed in obesity and T2D, suggesting its involvement in adipose tissue inflammation and insulin resistance." (PMID 39627194, 2024). "Inflammatory chemokines, such CXCL8 (chemokine ligand 8), are elevated in obesity and insulin resistance and contribute to the recruitment of immune cells into metabolic tissues, fostering chronic low-grade inflammation." (PMID 39627194, 2024). "Mouse CXCL1 and CXCL2 (CXCL1/2) are well-established functional homologs of human CXCL8 (IL8), whose expression is also induced by NF-κB36–38 in obesity and insulin resistance." (PMID 34686752, 2021). "IL-8 (CXCL8) is a proinflammatory chemokine which mediates the crosstalk between obesity and cardiovascular disease." (PMID 33292260, 2020). "An interaction of borderline significance (P = 0.072) between carbon black exposure and overweight or obesity for affecting CXCL8 expression in hCAECs was observed in this study." (PMID 32993720, 2020). "First, adipose tissue is an important source of proinflammatory cytokines including tumor necrosis factor-alpha (TNFα), interleukin-(IL)-6 (IL-6) and IL-8 (CXCL8), which contribute to obesity-associated ‘smoldering’ inflammation." (PMID 31234447, 2019). "We show that in prostate cancer CXCL1 expression is obesity dependent, while CXCL8 expression is obesity independent in malignant tumour cells." (PMID 27241286, 2016). "Here we provide evidence that cancer-induced CXCL8 and obesity-dependent CXCL1 gradients regulate ASC trafficking in the context of prostate cancer." (PMID 27241286, 2016).
Obesity (continued). "Additionally, genes involved in white fat differentiation and adipogenesis pathways were downregulated by OJ consumption, including KLF4 (−2.3), RIPK1 (−1.7), PLIN2 (−1.99), and CXCL8 (−34.43); genes found as overexpressed in obesity." (PMID 41169019, 2025). "There are several possible mechanisms: First, while adiponectin promotes the differentiation of bone mesenchymal stem cells (BMSCs) in bone marrow to osteoblasts via CXCL1 and CXCL8 up-regulation, subjects with obesity are prone to obtain lower levels of adiponectin." (PMID 40455716, 2025). "Among the TGBOD, CXCL8 was found to be down-regulated in the treatment group, which is consistent with previous studies showing that the expression of CXCL8 has a positive relationship with obesity." (PMID 38570815, 2024). "CXCL8 plays a key role in the pathophysiology of obesity, driving liver inflammation and injury." (PMID 39334887, 2024). "Higher expression levels of CXCL1 and CXCL8 were identified as independent risk factors for significant weight gain, and CXCL1 and TNF were identified as independent risk factors for new-onset postoperative obesity." (PMID 38965454, 2024). "Venn diagram analysis revealed that seven DEGs (CXCL8, MLXIPL, CREB3L1, EGR1, NOTCH3, ACTA2, and SERPINE1) were associated with both obesity and diabetes-associated pathways, including non-alcoholic fatty liver disease, insulin resistance, thermogenesis, and apelin signaling pathways." (PMID 38570815, 2024). "Besides, hypertension and diabetes are linked by CXCL8, HLA-B, and KANSL1; diabetes and obesity are linked by TRIM26 and MMP8; hypertension and obesity are linked by PLA2G7, FSTL3, STC2, and BCL2A1." (PMID 36685671, 2023). "Stratification analysis showed a significantly increased level of CXCL8 expression associated with overweight or obesity in CBPs (RQ = 2.58, P = 0.046), but not in controls (P = 0.57)." (PMID 32993720, 2020). "Our results propose that CXCL8 may be a potential target of obesity in these cells." (PMID 35894174, 2022). "CXCL8 may mediate the downregulation of adiponectin in obesity." (PMID 35211112, 2022). "In obesity, adipose tissue can release proinflammatory cytokines (e.g., TNF, IL-6), CXCL8, and adipokines (e.g., leptin), dysregulating leukocyte trafficking." (PMID 40718478, 2025). "Other chemokines include but not limited to CCL2 (MCP-1), CCL3 (MIP-1α), CCL4 (MIP-1β), CCL19, CXCL1, CXCL8 or IL-8, CXCL10, and CXCL12 also play an important role in obesity and cancer immunotherapy." (PMID 40863244, 2025). "Human and animal studies have shown CXCR1/2 agonists (e.g., CXCL8, CXCL5 in T1D patients, CXCL1 in mice) to be correlated with obesity and insulin resistance." (PMID 40718478, 2025). "A whole-transcriptome study revealed differentially expressed target genes important in obesity and diabetes-related pathways such as MLXIPL, CREB3L1, EGR1, ACTA2, SERPINE1, NOTCH3, and CXCL8." (PMID 38570815, 2024). "This review provides an in-depth analysis of specific chemokines involved in the development of obesity, including C-C motif chemokine ligand 2 (CCL2), CCL3, CCL5, CCL7, C-X-C motif chemokine ligand 8 (CXCL8), CXCL9, CXCL10, CXCL14, and XCL1 (lymphotactin)." (PMID 39334887, 2024). "Thus, CXCL8 may mediate the down regulation of adiponectin in obesity." (PMID 34054797, 2021). "The proinflammatory cytokines TNF-α and IL-18 are known to be elevated in obesity/T2D while IL-8 or CXC chemokine ligand (CXCL)-8 is an inflammatory protein and increased circulatory numbers of IL8-expressing monocytes were also reported in human obesity." (PMID 27980459, 2016). "Combined, our results suggest that in patients, CXCR1 expressed in ASCs in vivo, and possibly CXCR2, direct ASC trafficking towards CXCL8 gradient activated in cancer and CXCL1 gradient in addition activated in obesity." (PMID 27241286, 2016).